CD24 (CD24 molecule)
Diseases named in the same sentence as CD24 in open-access papers (continued):
Sharing a sentence is not in itself a finding about the gene and the disease.
ovarian carcinoma (continued). "In the context of ovarian carcinoma, CD24 is highly expressed." (PMID 37045827, 2023). "Moulla reported that high grade ovarian carcinomas could express higher level of CD24, when compare with low grade ovarian carcinomas." (PMID 37359556, 2023). "In another study, cytoplasmic CD24 was associated with poor survival in ovarian cancer; however, membranous CD24 did not appear to impact patients’ survival." (PMID 38201468, 2023). "Indeed, increased cytoplasmic expression of CD24 is a marker of reduced survival in patients with serous adenocarcinoma of ovarian cancer and is one of the biomarkers of epithelial ovarian cancer." (PMID 36741380, 2022). "However, tumor expressed CD24 in ovarian cancer prevents macrophage-mediated phagocytic tumor clearance and promotes immune evasion by interacting with the inhibitory receptor sialic-acid-binding Ig-like lectin 10 (Siglec-10) expressed on TAMs." (PMID 36035994, 2022). "An analysis of exosomes obtained from 21 patients serum with ovarian cancer showed that CD24 protein expression was significantly correlated with the development of OC, suggesting that CD24 protein may also be used as a biomarker of OC." (PMID 36548867, 2022). "In addition, the CD24/Siglec-10 signal also provide a target for restoring the phagocytosis of peritoneal resident TAMs in ovarian cancer." (PMID 36035994, 2022). "CD47 expression is predictive of disease stage and prognosis in patients with ovarian cancer, whilst one study identified ovarian tumours to express the highest level of CD24 of all cancer types analysed, with its expression inversely correlating with patient RFS." (PMID 35020853, 2022). "However, the CD44+/CD24- phenotype in ovarian cancer cells determines the CSC properties of newly propagated and invasive tumors, and ovarian cancer patients with this phenotype exhibit enhanced recurrence and shorter progression-free survival." (PMID 34064635, 2021). "Consequently, targeting CD24 with a monoclonal antibody in preclinical ovarian cancer cell line models has been shown to decrease cell proliferation and tumor growth." (PMID 33260974, 2020). "The chip was used to detect CA125, EpCAM, and CD24 in the plasma of ovarian cancer patients." (PMID 33322519, 2020). "Furthermore, CD44+/CD24- expression correlates with increased recurrence rate and reduced progression-free survival in ovarian cancer patients." (PMID 35582216, 2020). "For example, a nanoplasmonic exosome (nPLEX) assay was developed based on transmission surface plasmon resonance (SPR) and arrays of periodic nanoholes functionalized with antibodies to identify exosomal CD24 and EpCAM expression in ascites fluid from ovarian cancer patients." (PMID 32226524, 2020). "Lastly, CD24 is another well-known selectin ligand that is important in ovarian cancer progression." (PMID 32785160, 2020). "SWA11mAb targeting CD24 effectively retarded the growth of lung and ovarian carcinoma xenografts." (PMID 32765491, 2020). "In summary, we developed a new anti-CD24 CAR against ovarian cancer." (PMID 30717444, 2019). "Additionally, NK-92 cells equipped with our novel anti-CD24 CAR were highly effective against patient-derived primary ovarian cancer cells." (PMID 30717444, 2019). "One potential interpretation may relate to the fact that only intracellular CD24 appears to affect ovarian cancer survival." (PMID 31244889, 2019). "CD44, CD24, CD133, CD117, and EPCAM have been reported to be associated with ovarian cancer." (PMID 30581772, 2018).
ovarian carcinoma (continued). "Several putative ovarian cancer stem cell markers, such as CD24, CD44, CD133, SOX2, SSEA have been proposed, but the definition of their phenotypical features remains highly variable in the various studies, probably due to the consistent phenotypic and functional plasticity of these cells." (PMID 29389895, 2018). "Thus, we evaluated the level of RalA activation in CD24 high populations relative to CD24 low populations, as expression of this marker seems to follow a spectrum in ovarian cancer cells." (PMID 29047224, 2017). "They determined whether CD24, which is a currently established marker for ovarian cancer prognosis, is present within exosomes." (PMID 29262670, 2017). "In agreement with the hypothesis of a CD24/STAT3 interplay in ovarian cancer stemness, CD24+ OCSC exhibit increased levels of STAT3 phosphorylation and of STAT3-dependent expression of stemness factors such as Nanog and c-Myc." (PMID 28320418, 2017). "Furthermore, CD24+ stem-like cells detected in ovarian cancer also exhibited enhanced chemoresistance." (PMID 24955581, 2014). "Recently, CD24+ ovarian cancer cells exhibiting EMT phenotype were reported." (PMID 23947765, 2013). "Expression of CD24 affected metastasis and represented poor prognosis in ovarian cancer." (PMID 23509802, 2013). "Ovarian cancer cell lines show high expression of CD24 as they have epithelial phenotype." (PMID 22693526, 2012). "Increased CD24 correlates with aggressive behavior in renal cell carcinoma, glioma, non-small cell lung cancer, breast cancer, prostate cancer and ovarian cancer." (PMID 21676268, 2011). "Therefore, we hypothesized that CD24 upregulates MET expression by regulating miRNA expression in ovarian cancer cells." (PMID 38030594, 2024). "Therefore, CD24-regulated miRNAs may play roles in manifesting the CSC phenotypes in ovarian cancer cells." (PMID 38360723, 2024). "However, although MET contributes to ovarian cancer progression, its roles in ovarian CSCs and its relation with CD24 remain unknown." (PMID 38030594, 2024). "CD24 could be found in the cytoplasm inside MVBs and released into the extracellular environment via exosomes, it is correlated with more aggressive forms of ovarian carcinoma so it worse the prognoses and shorten patients' survival times." (PMID 37497408, 2023). "CD24 could protects ovarian cancer cells from macrophage attack in vitro, and in vivo." (PMID 37359556, 2023). "Additionally, surgeons reported that CD24-targeted intraoperative fluorescence image could be a promising application in improving debulking surgery of ovarian cancer." (PMID 37359556, 2023). "In ovarian cancer and triple-negative breast cancer, tumor cells evade clearance by macrophages through over-expression of CD24 that interacts with Siglec-10 in TAMs, and its blockade augments the phagocytosis of CD24-expressing tumors leading to a reduction of tumor growth." (PMID 34447383, 2021). "Surprisingly, CD24 amplification in ovarian cancer does not associate withOS." (PMID 31244889, 2019). "CD24 can also be found in the cytoplasm inside MVBs and released into the extracellular environment via exosomes, in which case it is correlated with more aggressive forms of ovarian carcinoma, worsening the prognoses and therefore, shortening patients’ survival times." (PMID 24460816, 2014). "Interestingly, studies reported that CD44+CD24− cells from epithelial human ovarian cancer cell lines have properties of ovarian CSCs/TICs, whereas another study reported that CD24+ cells from ovarian cancer patient samples are a subpopulation of ovarian CSC/TICs." (PMID 23528891, 2013). "In ovarian cancer models, PPAB001 has shown enhanced efficacy compared to therapies that block only CD47 or CD24 individually." (PMID 40330466, 2025). "CAR-NK therapies targeting ovarian cancer, with MSLN-, CD24- and αFR-targeted CAR-NK cells demonstrating strong preclinical efficacy, show promise." (PMID 40705122, 2025).
ovarian carcinoma (continued). "According to our results, CD24 expression induced the downregulation of miR‐181a, contributing to MET overexpression in serous types of ovarian cancer cell lines, OV90 and SK‐OV‐3 cells." (PMID 38030594, 2024). "The CSC phenotype was assessed for primary and immortalized ovarian cancer cells based on the expression of CD133, CD24, and c-kit molecules." (PMID 38791431, 2024). "A tissue immunostaining‐based survival analysis examined how CD24 and MET expression affected ovarian cancer patient survival." (PMID 38030594, 2024). "Analysis of a combination of CD24 and EpCAM with CA125 as tumor-dervied exosomal markers improved the accuracy for early diagnosis of ovarian cancer." (PMID 38796525, 2024). "CD24 affects the EMT via the activation of the Akt- and ERK-signaling pathways in the cisplatin-resistant ovarian cancer cell line Caov-3." (PMID 38791431, 2024). "CD24 expression was manipulated in ovarian cancer cell lines, TOV112D (CD24-low) and OV90 (CD24-high) cells, using gene transduction to confirm CD24-dependent upregulation of miR-199-3p, 34c, 199a-5p, 130a, 301a, 214, and 34b*." (PMID 38360723, 2024). "This study showed the relationship between CD24-regulated miRNAs and CSC phenotype acquisition in ovarian cancer and how CD24 contributes to CSC phenotype acquisition in ovarian cancer via miR-130a and 301a-dependent downregulation of CDK19." (PMID 38360723, 2024). "This study demonstrated that CD24 induced the expression of miR-130a and 301a via Src or FAK-mediated STAT4 and YY1 phosphorylation in ovarian cancer cells, which led to cellular quiescence-like state and chemoresistance." (PMID 38360723, 2024). "Several established ovarian cancer stem cell markers, including CD44, CD117, CD133, CD24, and ALDH have been used to identify ovarian cancer stem cell populations." (PMID 39224110, 2024). "In ovarian cancer, CD24 and EGFR have been characterized in exosomes and proposed as potential biomarkers for ovarian cancer." (PMID 36675253, 2023). "NK cells were transduced with an anti-CD24 CAR containing a highly active single-chain variable fragment (scFv) against CD24, which specifically killed patient-derived ovarian cancer cells." (PMID 37894750, 2023). "The novel anti-CD24-CAR-NK-92 cells showed the ability to eliminate ovarian cancer SKOV3 and OVCAR3 cells, which express high levels of CD24, completely when co-incubated with them." (PMID 38137380, 2023). "An enriched population of cancer stem cells with stemness markers like CD24, CD44, CD117, and CD133 are often found in ovarian cancer spheroids." (PMID 37776168, 2023). "Unlike most of the published reports showing that several surface markers used to identify ovarian CSCs, such as CD24, CD44, CD117, and CD133, we have unveiled the ACTL6A had poor prognosis and correlated enrichment of CSCs in ovarian cancer." (PMID 36768349, 2023). "Niko P. Bretz scrutinised CD24 expression in A549 lung cancer, SKOV3ip ovarian cancer, and HS683 and SNB19 glioblastoma cells, and discovered that Src, activated by CD24 tyrosine, phosphorylates STAT3 signalling molecules, which causes the activation of STAT3." (PMID 38137380, 2023). "Also, it is reported that liposomal cisplatin with a red fluorescent substance cyanine 5.5 and mortified with anti-CD24 monoclonal antibody, called (CD24-GL-CDDP-Cy5.5) could improve of the delivery of cisplatin via increasing the targeting the CD24 positive ovarian cancer cells." (PMID 37359556, 2023). "Moreover, all samples tested positive for CD24 in ascites-derived exosomes even when the corresponding tumors were negative, which suggests that the ascites exosome test could be a sensitive method for diagnosing ovarian cancer." (PMID 37215442, 2023). "The following surface and intracellular markers have been discovered in ovarian cancer stem cells: aldehyde-dehydrogenase (ALDH), CD133, CD44, CD177, CD24, and EpCAM29." (PMID 37497408, 2023).
ovarian carcinoma (continued). "Similar to CD47, CD24 is overexpressed in a variety of solid tumors, including triple-negative breast cancer (TNBC), ovarian cancer, and GBM." (PMID 36013403, 2022). "Some anti-CD24 drugs targeting tumors have been put into clinical trials, such as SWA11 (mAb), which is related to ovarian cancer and pancreatic cancer, and rG7S-MICA (mAb), which is related to liver cancer." (PMID 36013403, 2022). "In hepatocellular and ovarian carcinoma, a link between EMT and high CD24 protein levels has been described." (PMID 34293822, 2022). "First, a large number of literatures suggest that CD44, CD117, CD133, CD24, aldehyde dehydrogenase (ALDH) and other markers can be used to investigate cancer stem cells in certain ovarian cancer types." (PMID 36046821, 2022). "Remarkably, the expression of standard ovarian cancer CSC markers, such as CD24 and CD44, gradually increases along the EMT trajectory." (PMID 34830900, 2021). "Accumulating evidences had demonstrated that CD24 was involved in epithelial–mesenchymal transition (EMT) and its increased expression was correlated with poor prognosis in patients of epithelial ovarian cancer." (PMID 33135729, 2020). "From them, CK19, MUC1, CD24, CD44, TIMP1, and CXCR4 appeared, characterizing the ovarian cancer circulating population." (PMID 32423054, 2020). "A dual-CAR approach targeting CD24 and MSLN with engineered NK cells has been tested in vitro against ovarian cancer cell lines and patient-derived primary tumour samples with promising results." (PMID 32937961, 2020). "Other than mucins, important known selectin ligands in ovarian cancer include glycosaminoglycans like heparan sulfate and chondroitin sulfate, and some other glycoproteins like CD44 and CD24." (PMID 32785160, 2020). "CD24-CAR-NK cells are activated following specific binding to the SWA11-antigenic recognition site, and elicit cytotoxic activity against CD24+ tumor cell lines (Skov-3, OVCAR3) and patient-derived primary ovarian cancer cells." (PMID 33260974, 2020). "The phenotype of CD44+/CD24− in ovarian cancer cells has been reported to exhibit CSC-like properties of enhanced differentiation, invasion, and resistance to chemotherapy, while CD44+/CD24+/Epcam+ exhibited stem cell characteristics in other reports." (PMID 30818864, 2019). "Here, we investigated the copy number status and expression level of CD24 in BRCA, ovarian cancer, lung cancer, and prostate cancer." (PMID 31244889, 2019). "CD117 (c-kit), CD44, CD24, and CD133 are usually expressed in solid tumors including ovarian cancer." (PMID 30581772, 2018). "In ovarian cancer xenografts, cancer cells co-expressing EpCAM and CD44 or CD24 had stemness properties with resistance to doxorubicin and cisplatin." (PMID 30551640, 2018). "Various specific markers including ALDH1/2, CD133, CD117, CD24, CD34, CD44, CD133, EpCAM, LGR5 and LY6A have been employed for isolation and characterization of ovarian CSCs from ovarian cancer cell lines, patients’ tumors and ascites." (PMID 30121075, 2018). "In our previous studies in vivo, we showed a significant increase in CSCs: CD24, CD34, CD44, CD117, ALDH1 and OCT4, in tumors collected from animals bearing orthotopic ovarian cancer followed by treatment with cisplatin." (PMID 29190952, 2017). "First identified in the hematopoietic system, CSCs have been successively identified in many different types of tumors (including ovarian cancer), by several putative markers, such as CD44, CD24, EpCAM, CD133, CD117, ALDH1." (PMID 29187221, 2017). "In ovarian cancer cells SKOV3 and OVCAR3, originated from human ovarian cancer ascites cells, expression of either CD44, CD24 or CD133 markers is related to drug-resistance, a stem-like characteristics of cancer cells." (PMID 27655682, 2016). "With the intent to isolate CSC ovarian cancer, 37 primary tumor samples were evaluated for the expression of CXCR4/CD133 and CD44/CD24." (PMID 26020117, 2015).
ovarian carcinoma (continued). "TICs have been identified in both human and murine ovarian cancers by sorting for CD44, CD133, CD117, CD24, ALDH1, and SCA1 expression alone or in combination." (PMID 24672774, 2014). "The knockdown of CD24 decreased cell viability by activation of apoptosis in ovarian cell line SKOV3 in vitro and also suppressed tumor growth in nude mice bearing ovarian cancer in vivo." (PMID 23509802, 2013). "The knockdown of CD24 decreased cell viability by in vitro activation of apoptosis in ovarian cell line SKOV3, also suppressing tumor growth in nude mice bearing ovarian cancer in vivo." (PMID 23902592, 2013). "According to published data on different ovarian cancer cell lines, there appear to be substantial variations in proportions of CD44 and CD24." (PMID 22693526, 2012). "In support of these results, another study in ovarian cancer observed great variation in CD44 and CD24 expression in almost all patients ranging from 2.2%–88.2% and 3.2%–86.7%, respectively." (PMID 22693526, 2012). "It is therefore not surprising that stem cell properties have been reported in ovarian cancer cells isolated using different cell surface markers, including CD44, CD133, or CD24." (PMID 21904548, 2011). "We confirmed a number of ovarian cancer genes previously identified by GEM, for example, CD24, HE4, PRAME, B-factor (properdin), and, where our studies overlap, the data are highly consistent, despite the difference in methodology." (PMID 14760385, 2004). "Therefore, the expression of CD24, miR-130a, miR-301a, and CDK19 was analyzed with 53 cases of ovarian cancer patient tissues." (PMID 38360723, 2024). "This study investigated the correlation between CD24 and MET in ovarian cancer and whether CD24 induced MET upregulation via miRNA regulation, which is associated with CSC features." (PMID 38030594, 2024). "Subsequent investigations revealed that CD24 overexpression occurs in other types of tumors, not limited to breast and ovarian cancer, and that TAMs exhibit high levels of Siglec-10." (PMID 38273373, 2024). "Our immunohistochemistry analysis showed that the co‐expression of CD24 and MET was associated with poorer patient survival in ovarian cancer than those without." (PMID 38030594, 2024). "Conversely, in ovarian cancer and triple-negative breast cancer (TNBC), sialylated CD24 on the surface of tumor cells serves as a “don’t eat me” signal by binding to Siglec-10 on macrophages, thereby preventing the clearance of cancer cells and facilitating tumor progression." (PMID 39791710, 2024). "In this study, we first hypothesized that CD24 induces MET expression, contributing to the manifestation of CSC phenotypes in ovarian cancer." (PMID 38030594, 2024). "In ovarian cancer, the CD24-positive population of cancer cells showed significantly greater tumor initiation in a transgenic murine model than the CD24-negative population." (PMID 38360723, 2024). "Notably, CD24 is most highly upregulated in tumor cells found in triple-negative breast cancer (TNBC) and ovarian cancer." (PMID 37484024, 2023). "CD24 is highly expressed in invasive ovarian cancers but not in normal tissue or benign ovarian tumors, which is related to the reduced survival rate of patients with ovarian cancer." (PMID 37894750, 2023). "Some cancers, like blood cancers, tend to be highly sensitive to CD47 signaling blocking therapies but not to CD24 signaling inhibitors, while others, such as ovarian cancer, are more responsive to CD24 signaling blocking therapies." (PMID 37484024, 2023). "In order to scrutinize the initiating cell status and identity of iOVCAR-3-OSKM cells, we evaluated the expression levels of several ovarian cancer initiating cell (OCIC) markers that previously reported like CD133, CD177, CD24, CD44, ABCG2, and ALDH1 in cells." (PMID 36085021, 2022).